IL1B (interleukin 1 beta)
Diseases named in the same sentence as IL1B in open-access papers (continued):
Sharing a sentence is not in itself a finding about the gene and the disease.
intestinal inflammation (39 papers, 2009 to 2026). "Intestinal inflammation in human and animals has been widely shown to be associated with changes in contractility and IL-1β was found to inhibit both initial and sustained contraction and LC20 phosphorylation stimulated by acetylcholine in the presence of an M2 receptor antagonist." (PMID 25723491, 2015). "Proinflammatory cytokines, including TNF-α, IL-6, IL-1β, and IL-17, play an important role in drug-induced and spontaneous intestinal inflammation." (PMID 37660913, 2023). "pointed out that LAB can inhibit p-IκBα, interfere with the NF-κB initiation, and represses the IL-1β and IL-6 levels in a mouse intestinal inflammation model." (PMID 35310848, 2022). "Consistent with such a possibility, it was recently demonstrated that the inhibition of the IL-1β-induced increase in intestinal TJ permeability prevented the dextran sodium sulfate (DSS)-induced intestinal inflammation." (PMID 34759934, 2021). "Intestinal inflammation involves immune cells of both the innate and adaptive immune systems, and is characterized by marked increases in pro-inflammatory cytokines IL-1β, TNF-α, IL-12, IL-17, IL-1α and INF-γ." (PMID 32998266, 2020). "Canakinumab has been reported to induce adverse events, such as nasopharyngitis, upper respiratory infections, and gastroenteritis, presumably due to the effects of blocking the actions of the proinflammatory cytokine IL-1β." (PMID 26590045, 2015). "Interestingly, rectal administration of 0.3% NaOH solution induced intestinal inflammation, colon shortening, and upregulation of inflammatory cytokines IL-1β and IL-6." (PMID 39737965, 2024). "Taken together, understanding the potential opposing roles of IL-1 agonists, such as IL-1α and IL-1β, during the initiation and progression of chronic intestinal inflammation, will shed further light on precise therapeutic modalities that will lead to more efficacious treatment of patients with IBD." (PMID 23847622, 2013). "An alternative hypothesis to support the dichotomous role of IL-1 in IBD is that IL-1α and IL-1β possess opposing roles during the progression of chronic intestinal inflammation." (PMID 23847622, 2013). "Meanwhile, the levels of inflammatory cytokines (e.g., IL-6, IL-1β and TNF-α) were elevated, indicating the presence of intestinal inflammation." (PMID 40427600, 2025). "Stress from separating piglets from their sows, along with dietary and environmental changes, can induce transient intestinal inflammation in piglets, characterized by increased pro-inflammatory cytokines TNF-α, IL-6, and IL-1β." (PMID 40336817, 2025). "Contrary to the anti-inflammatory cytokines, IL-1β, IL-6, and TNF-α, as pro-inflammatory cytokines which have been reported in the intestinal inflammation occurrence, were dose-dependently decreased by SSPs administration." (PMID 35359717, 2022). "Although 4-methylesculetin was not reported as an inhibitor of the NF-κB signaling pathway, a reduction of pro-inflammatory cytokines production, such as IL-1β, IL-6, IL-17, and TNF-α was described in experimental models of intestinal inflammation at same doses." (PMID 37111267, 2023). "Intestinal inflammation is related to higher TNF-α, IL-1β, and IL-6 levels." (PMID 37111225, 2023). "NF-κB proteins are a major family of transcription factors, composed of subunits of the Rel family, p50 and p65, which play a key role in the regulation of proinflammatory gene transcription such as IL-1β, IL-6, TNF-α, Cox-2, iNOS, and adhesion molecules in the process of intestinal inflammation." (PMID 29853790, 2018). "Animal studies have suggested that lycopene could not only suppress the expression of pro-inflammatory factors like IL-1β, IL-6, IL-8 and TNF-α, but also stimulate the production of anti-inflammatory cytokines (such as TGF-β, IL-10), so as to reduce intestinal inflammation." (PMID 37608273, 2023).
intestinal inflammation (continued). "Recent studies have shown that physiological concentrations of IL-1β and TNF-α significantly increase intestinal epithelial TJ permeability, and inhibiting the IL-1β-induced increase in intestinal TJ permeability prevents sodium dextran sulfate (DSS)-induced intestinal inflammation." (PMID 37523400, 2023).
vasculitis (39 papers, 2013 to 2026). "IL-1β expression was significantly associated with vasculitis-related changes (p = 0.0028), with >50% nuclear positivity exhibiting a high odds ratio (OR = 25.0, 95% CI = 2.60–240.34), indicating potential involvement in vascular inflammatory damage." (PMID 41009699, 2025). "Insights from mouse models suggested that IL-1α, IL-1β, and their receptors are essential for the development of KD-associated vasculitis." (PMID 40308588, 2025). "Mice with LCWE-induced KD vasculitis showed increased frequencies of MPAs associated with elevated levels of circulating IL-1B." (PMID 37279077, 2023). "Vasculitis causes tissue injury and releases cytokines like IL-6, IL-1β, and TNFα, which in turn trigger endothelial exocytosis and so on." (PMID 35061142, 2022). "In LCWE-injected mice, this was associated with decreased severity of LCWE-induced KD vasculitis and significant reductions of both tissue Caspase-1 activity and systemic IL-1β levels." (PMID 34403365, 2021). "Exaggerated responses to IL-1β, however, are associated with potentially deleterious effects; and excessive IL-1β activity is associated to vasculitis and thrombosis." (PMID 32477265, 2020). "Interestingly, vasculitis—a morphologic indicator of acute immune damage—was significantly associated only with IL-1β expression." (PMID 41009699, 2025). "It recruits inflammatory cells (e.g., Monocytes and neutrophils) via the CCRI pathway through its receptor CCR2, and activates the Dectin-2/NLRP3 inflammasome to induce IL-1β, driving vasculitis in KD models." (PMID 40455761, 2025). "IL-1β nuclear expression showed strong associations with ACR (p = 0.0001), inflammation, vasculitis, and immune/endothelial markers (all p < 0.003)." (PMID 41009699, 2025). "Macrophages and T-cells within these vasculitis lesions secrete a spectrum of proinflammatory cytokines which importantly include interleukin-1 beta and interleukin-6." (PMID 36983848, 2023). "Platelets release mediators that boost the expression and secretion of proinflammatory cytokines by human monocytes, such as IL-1B, which are highly inflammatory and important mediators of cardiovascular diseases, including KD vasculitis." (PMID 37279077, 2023). "We also observed increased frequencies of MPAs and higher circulating levels of IL-1B during LCWE-induced KD vasculitis, which were reduced in thrombocytopenic mice." (PMID 37279077, 2023). "Previous studies indicate that in LCWE-induced KD vasculitis, monocytes and macrophages are the main sources of IL-1B, while neutrophils and eosinophils also express transcripts (Il1b, Nlrp3, Casp1, and Pycard) and have the capacity to produce IL-1B." (PMID 37279077, 2023). "Some Th1-related cytokines are also released during this process, and include interferon-γ, IL-1β, IL-6 and IL-8, which further exacerbate vasculitis and tissue injury." (PMID 35183233, 2022). "The promotion of IL-1β-induced KD vasculitis in mice led to the initiation of clinical trials assessing the effect of anakinra for blocking IL-1β as a secondary therapy option to treat children with IVIG-resistant KD." (PMID 35153622, 2022). "IL-1β targeting with canakinumab, or its cell surface receptors with Anakinra, are proposed treatments for a variety of conditions including vasculitis and diabetic foot ulcers." (PMID 35154073, 2021). "In a Candida albicans-derived substances (CAD) mice model, another KD vasculitis model, IL-1β, IL-6, and TNF-α are reported to be upregulated." (PMID 23606968, 2013). "Both IL-1β and NLRP3 deficiency could protect mice from the induction of vasculitis in these models." (PMID 40308588, 2025). "Overall, these results support the notion that the increased platelet number promotes MPA formation and drives further IL-1B release in LCWE-induced KD vasculitis, which may exacerbate the development of cardiovascular lesions." (PMID 37279077, 2023). "MPAs promote increased IL-1B production during LCWE-induced KD vasculitis." (PMID 37279077, 2023).
vasculitis (continued). "MicroRNA-223 (miR-223) is a negative regulator of NLRP3 activity and IL-1β production, and its expression has been reported to be upregulated during acute human KD; however, the specific role of miR-223 during KD vasculitis remains unknown." (PMID 34026693, 2021). "We hypothesize that intense IL-1β production during LCWE-induced KD vasculitis induces miR-223 expression as a negative regulatory feedback loop to suppress IL-1β function and further development of vasculitis." (PMID 34026693, 2021). "Together with IL1-β, the IL-1α plays an important role in the development of KD vasculitis." (PMID 34362028, 2021). "Activated macrophage produces IL-1β, a master cytokine of systemic inflammation, which has a vital function in auto-inflammatory diseases and has been more recently connected to KD vasculitis." (PMID 29721174, 2018). "In addition, alleviating ER stress in mice by deletion or pharmacological inhibition of ER resident endoribonuclease IRE1 also reduces LCWE-induced KD vasculitis as well as caspase-1 activity and IL-1β production, highlighting the importance of ER stress pathways in KD progression." (PMID 38020895, 2023). "Besides, S100A12 could promote vasculitis by stimulating the production of IL-1β, which directly induces CA endothelial cell dysfunction and impacts the risk of the formation of CAL in children with KD." (PMID 36829193, 2023). "However, the contribution of ER stress to NLRP3 activation and IL-1β secretion remains unknown in KD vasculitis." (PMID 35167493, 2022). "Biallelic hypomorphic variants of OTULIN underlie an autoinflammatory disorder with multiple phenotypes including vasculitis, and high levels of NF-κB, TNF, IL-1β, and IL-17 production have also been observed." (PMID 39403923, 2024). "It found that the level of miR‐223 was increased during LCWE‐induced KD vasculitis, but miR‐223 appeared to reduce inflammation in vascular tissue by inhibiting NLRP3 activation and IL‐1β production." (PMID 37506144, 2023). "Studies in experimental murine models of KD vasculitis have confirmed those observations and further demonstrated the deleterious role of NLRP3 overactivation and enhanced IL-1β production during KD." (PMID 34026693, 2021). "LCWE-induced KD vasculitis is NLRP3 dependent, and it has been previously shown that miR-223 regulates NLRP3 activation and IL-1β production." (PMID 34026693, 2021). "Collectively, our data reveal a previously unappreciated role of miR-223 in regulating innate immune responses and in limiting KD vasculitis and its cardiovascular lesions by constraining the NLRP3 inflammasome and the IL-1β pathway." (PMID 34026693, 2021). "The LCWE-induced KD murine model of vasculitis is dependent on NLRP3 inflammasome activation, and as expected, IL-1β levels were increased in the serum of LCWE-injected mice compared with control PBS-injected mice." (PMID 34403365, 2021). "This study revealed the effects of LA on endothelial cell activation, NLRP3, IL-1β, TNF-α, IL-32, and CCL-2, VCAM-1, MCP-1, and the spleen tyrosine kinase (Syk)--p38/JNK signaling axis and its effect on vasculitis in rats." (PMID 30158835, 2018). "Using a mouse model of LCWE-induced vasculitis, which is dependent on IL-1β and inflammasome activation, we observed that quercetin significantly inhibited the cardiovascular lesions in the LCWE-induced vasculitis mouse model." (PMID 28148962, 2017). "Our study aimed to evaluate the expression patterns of MMP2, MMP9, and IL-1β in human endomyocardial biopsies and to correlate them with established histopathological parameters, such as ACR, AMR, inflammation, vasculitis, the Quilty effect, and immune marker expression." (PMID 41009699, 2025). "The current study noted that serum PDGF-CC levels in KD patients were positively correlated with WBC, N%, IL-2, IL-12p70, TNF-α, and IL-1β and negatively correlated with L%, supporting the hypothesis that PDGF-CC exerts its effect in the KD vasculitis." (PMID 38273388, 2024).
vasculitis (continued). "The results demonstrated that HXTLF could inhibit the phosphorylation of AKT1, IKK, and NF-κB proteins, inhibit NETs formation, and reduce IL-1β concentration, indicating that AKT1 exerts a vital role in the treatment of vasculitis after HXTLF administration." (PMID 36034958, 2022). "Blocking the IL-1β pathway in mice, genetically or pharmacologically with either neutralizing antibodies or small-molecule inhibitors of NLRP3, prevents the development of LCWE-induced KD vasculitis." (PMID 35167493, 2022). "Given that P2RX7 is not essential for the development of GN and vasculitis in rats, this raises questions concerning the importance of IL‐1β." (PMID 35239186, 2022). "A recent single cell sequencing study revealed that monocytes are the main source of differentially expressed genes, and pro‐inflammatory genes such as IL‐1β and TNF‐α are significantly upregulated in PBMCs of KD patients, suggesting a pivotal role of monocytes/macrophages in KD vasculitis." (PMID 35582751, 2022). "To further determine if miR-233 dampens LCWE-induced KD vasculitis in WT mice by decreasing NLRP3 inflammasome activation and subsequent IL-1β production, we next quantified the circulating levels of IL-1β in LCWE-injected WT and mir-223−/y mice 1 week after LCWE injection." (PMID 34026693, 2021). "The enhanced cardiovascular lesions and KD vasculitis observed in LCWE-injected miR223−/y mice correlated with increased NLRP3 inflammasome activity and elevated IL-1β production, indicating that miR-223 limits cardiovascular lesion development by downmodulating NLRP3 inflammasome activity." (PMID 34026693, 2021). "Both IL-1β and ROS have been shown to result in tissue damage which may help drive the glomerulonephritis that is observed in some patients with MPO-ANCA vasculitis." (PMID 33015103, 2020). "Patients with ischemic symptoms have a higher concentration of mRNA coding for gamma interferon (γ-INF) and for IL-1b, suggesting that production of γ-INF is crucial for the development of vasculitis, particularly for the vascular occlusion, directly associated with the presence of γ-INF in situ." (PMID 24963300, 2014). "Thus, IL-1A, IL-1B, and IL1RN are considered attractive candidate genes for vasculitis." (PMID 31093510, 2019). "The present study preliminarily revealed the pharmacological mechanism of HXTLF in treating vasculitis using network pharmacology and in vitro experiments, implying that HXTLF might treat vasculitis by regulating AKT to inhibit the formation of NETs and induce IL-1β production in cells." (PMID 36034958, 2022). "We found that autophagy and mitophagy were impaired during LCWE-induced murine KD vasculitis and that genetic, nonpharmacologic and pharmacological modulation of autophagic flux decreased the severity of LCWE-induced cardiovascular inflammation by blocking NLRP3 activation and IL-1β secretion." (PMID 34403365, 2021). "It is possible that IL-1β production by myeloid cells is already maximal after LCWE-injection, and autophagy might not be sufficient to regulate NLRP3 activation; thus, blocking autophagy specifically in myeloid cells did not further promote vasculitis severity." (PMID 34403365, 2021).
AIDS (38 papers, 2009 to 2026). A syndrome resulting from the acquired deficiency of cellular immunity caused by the human immunodeficiency virus (HIV). "HIV is also a factor in the production of IL‐1β via transforming pro-IL-1β into bioactive IL-1β, a cytokine that is associated both with the progression to AIDS and higher CVD risk." (PMID 37982976, 2024). "In a study involving macaques with SIV-induced encephalitis, rapid progression to Acquired Immune Deficiency Syndrome (AIDS) correlated with an increase in IL-1β, IL-2, IL-6, IL-10, and TNF-α." (PMID 34784367, 2021). "Autoinflammatory diseases (AIDs) are heterogeneous disorders characterized by dysregulation in the inflammasome, a large intracellular multiprotein platform, leading to overproduction of interleukin-1(IL-1)β that plays a predominant pathogenic role in such diseases." (PMID 30999610, 2019). "Targeting CD177 represents a superior therapeutic strategy for NLRP3-AIDs, including IL-1β-refractory cases." (PMID 41898699, 2026). "Elevated levels of pro-inflammatory cytokines like IL-6, IL-1β, and TNF-α are associated with an increased risk of non-AIDS-related comorbidities such as cardiovascular diseases, neurocognitive disorders, and certain cancers." (PMID 40184131, 2025). "Numerous agents have been developed to target inflammasome products IL-1β and IL-18 for treating AIDs." (PMID 38666950, 2024). "Activation of the caspases in apoptosis or inflammation will induce programmed cell death or the release of inflammatory cytokines, including high-mobility group box (HMGB), IL-1β, and IL-18, which affect the development and progression of carcinomas and AIDs." (PMID 37006236, 2023). "A targeted approach with IL-1 receptor antagonist, anakinra, or human anti- IL-1β monoclonal antibody, canakinumab, have been proven to be efficacious in some AIDs." (PMID 36203564, 2022). "Taken together, our present data support the use of interventions targeting the IL-1β pathway or reduce β-glucan exposure as an adjunctive therapy to reduce non-AIDS–related comorbidities." (PMID 33630761, 2021). "Anakinra, an IL-1 receptor antagonist, canakinumab, an anti-IL-1β monoclonal antibody, and rilonacept, a soluble decoy receptor, represent efficient therapeutic approaches to control polygenic AIDs." (PMID 33708123, 2020). "In contrast, IL6 and TNFA were each increased in Pt-1 and Pt-2, respectively, while IL1B expression was increased in both HIV/AIDS patients’ brains compared to uninfected controls." (PMID 29037245, 2017). "Chronic inflammation and increased serum concentrations of IL-6 were found in HIV/AIDS, and functional in vitro assays indicated inhibitory effects of the pro-inflammatory cytokines IL-6 and IL-1β on IL-7-mediated signal transduction." (PMID 28582466, 2017). "Many of the immune mediators expressed at high levels in AIDS patients were also up-regulated in patients with CD (TNF-α, IL-1β, and IFN-γ) and have been implicated in the pathogenesis of CD." (PMID 26475133, 2015). "Consistent with IHC results, there was a significant increase in TNF-α (FC 7.11, p = 0.05) and IL-1β (FC = 4.27, p = 0.05) mRNA in AIDS patients compared to controls." (PMID 26475133, 2015). "In addition, three SNPs (IL1B rs1143623, STAT1 rs1467199 and STAT1 rs2066804) were associated with CD4+ T cell counts in patients with AIDS." (PMID 40331958, 2025). "Overactivated autoreactive immune cells such as T cells, DCs, and macrophages produce pro-inflammatory cytokines, including IL-1β, IL-6, IL-17, IL-23, COX-2, and iNOS, or chemokines that promote the recruitment of inflammation-associated cells in the affected areas of AIDs." (PMID 37006236, 2023). "By using microglia-derived cell lines, researchers observed that HIV promotes the synthesis of pro-IL-1β after 4 h post-infection and the release of this cytokine after 24 h; in agreement, brains of patients with AIDS showed high levels of IL-1β, IL-18 and caspase-1." (PMID 35783102, 2022).